IGF2 (insulin like growth factor 2)
Diseases named in the same sentence as IGF2 in open-access papers (continued):
Sharing a sentence is not in itself a finding about the gene and the disease.
tumor (continued). "Ectopic expression of miR-483 induces upregulation of IGF2 expression, as well as an increase in tumor cell proliferation, migration, invasion, and tumor colony formation in HCC." (PMID 35645336, 2022). "The transforming growth factor β (TGF-β)-signaling pathway plays an important role in cell differentiation, and IGF2 regulates the transcription of TGF-β-related pathway molecules in the epigenetic of tumor cells." (PMID 35465321, 2022). "Insulin-like growth factor 2 (IGF2), a multifunctional cell proliferation regulator, has an important role in promoting the differentiation and proliferation of embryonic and tumor cells." (PMID 35465321, 2022). "Pathological examination indicated a borderline phyllodes tumor of the breast, and immunohistochemistry suggested high expression of insulin-like growth factor-2 (IGF-2) in the tumor tissue." (PMID 35692391, 2022). "The CREB expression was more activated in the Mhigh subpopulation, directly affecting the expression of BCL-2, VEGF, NGF, and IGF2 in regulating tumor cell proliferation and survival or metastasis." (PMID 35740540, 2022). "We found that IGF2 expression is essential for liver fibrosis, inflammation, and tumor formation by triggering DNA damage, apoptosis, and proliferation." (PMID 35615981, 2022). "GPC3 and IGF-2 are potential drug targets that have significantly reduced tumour growth and prolonged survival in Phase 1 clinical trials and in animal models respectively." (PMID 36345011, 2022). "In accordance with the result that IGF-2 promotes the growth and proliferation of tumor cells, IGF-2R is considered to be a tumor suppressor gene during cancer occurrence and development." (PMID 36358907, 2022). "Our data shows promising insight into how impeding the IGF-2 pathway by reducing IR-A expression mitigates tumor growth." (PMID 35017650, 2022). "H19 imprinted maternally expressed transcript is located at chromosome 11p15.5 near the insulin-like growth factor 2 (IGF2) gene and encodes an approximately 2.3-kb lncRNA located in the cytoplasm that can act as a tumor-suppressor or oncogene." (PMID 36362925, 2022). "In detail, the expression levels of NCAM1 and IGF2 were significantly higher in tumor tissue compared to adjacent normal tissue from the same patient (P-value of < 0.01 and < 0.05, respectively)." (PMID 36284226, 2022). "We provide evidence that the protective role of FOXA1 on LUAD cells is highly dependent on induction of IGF2, which is a multifunctional growth factor that promotes tumor cell survival via activating IGF1R signaling cascade." (PMID 35974000, 2022). "In the current study, we demonstrated that methylation downregulated miR-543 in OvCa tissues and exosomes, and IGF2 is a critical direct downstream metabolic target involved in tumour proliferation." (PMID 35391781, 2022). "IGF2 decreased expression was detected in normal (5.5-fold, p < 0.01) and tumor tissue slices (3-fold, p < 0.001) compared to T0." (PMID 35884847, 2022). "The results obtained in the present work reveal a significant increase of IGF2 expression in patients with Gleason scores above 7 in comparation with controls or less aggressive phenotypes of the tumor." (PMID 35095996, 2021). "The oncofetal IGF2 mRNA-binding protein 1 (IGF2BP1) promotes tumor progression in a variety of solid tumors and its expression is associated with adverse prognosis." (PMID 33829040, 2021). "IGF2, together with transforming growth factor-α and matrix metalloproteinase-2, is used as a tumor staging marker and is also a key factor in the early stage of CRC." (PMID 34422629, 2021).
tumor (continued). "That is the case of miR-100 and miR-125b, which play a proven tumor suppressor role in hepatocellular carcinoma, by inhibiting IGF2 expression and activating AKT/mTOR pathway." (PMID 35095996, 2021). "Stimulating tumor cells with recombinant IGF2 limited isiPI3K efficacy and released treated cells from S phase arrest." (PMID 34067117, 2021). "In thyroid cancer, crosstalk between DDR1 and IGF-2/IR-A is responsible for tumor cell proliferation and invasion in 2D and 3D assays, and it is involved in the maintenance of tumor cell stemness." (PMID 33917302, 2021). "By comparing the transcriptional landscape of isiPI3K-sensitive tumor cells with that of their corresponding isiPI3K-acquired-resistant tumor cells, we found upregulation of insulin growth factor 2 (IGF2) in the resistant cells." (PMID 34067117, 2021). "MAFs can also augment tumor cell resistance to chemotherapy drugs by producing cytokines, including IGF2, IL-6 and IL-8." (PMID 34112258, 2021). "The IGF-2/IR-A loop activation has a recognized role in tumor progression, dedifferentiation, and therapeutic resistance." (PMID 33669363, 2021). "Cell 3 and its primary tumor 3 presented 28 genomic alterations in common, including gains of 4q12 (PDGFRA), an amplification of 11p15.5 (H19 and IGF2 genes), and a loss of 6p25.3 (DUSP22)." (PMID 33917394, 2021). "CRIS-D tumours are enriched for amplification of Chr11p15.5, encompassing the IGF2 locus, and exhibit activated IGF2 as well as FGFR signalling." (PMID 33673710, 2021). "High IGF2, FOXM1 and ETS1 levels also were significantly associated with lymphatic invasion and advanced tumor stage." (PMID 33407516, 2021). "IGF2 is highly expressed in a variety of tumor tissues, and activates the IGF1 signal pathway and promotes cancer progression on binding with IGF1R." (PMID 34335947, 2021). "IGF-2 was detected in the tumor and corresponding normal tissues and the measured high serum IGF-2 level led to a preoperative diagnosis." (PMID 33841338, 2021). "The oncofetal IGF2 mRNA-binding protein 1 (IGF2BP1) is a crucial regulator of tumor and stem cell fate and its elevated expression in a multitude of tumors is associated with poor prognosis." (PMID 33829040, 2021). "Mechanistically, we show that upon isiPI3K treatment, isiPI3K-sensitive tumor cells upregulate the expression of IGF2 to induce cell proliferation via the activation of the IGF1 receptor (IGF1R)." (PMID 34067117, 2021). "It has been reported that YAP, ALKBH5, IGF2 and other tumor suppressor elements can interact with ncRNA to inhibit tumor progression." (PMID 34188972, 2021). "H19 lncRNA was first described as a parentally imprinted lncRNA expressed from the IGF2 (insulin-like growth factor 2) locus that plays a role in fetal growth and tumor etiology, in part by controlling DNA methylation." (PMID 34316694, 2021). "The insulin receptor isoform A (IR-A) plays an increasingly recognized role in fetal growth and tumor biology in response to circulating insulin and/or locally produced IGF2." (PMID 34831367, 2021). "In hepatoblastoma cells, circHMGCS1 exerts its oncogenic role by sponging the tumor suppressing action of miR-503-5p, thus upregulating IGF2 and the PI3K-Akt signaling pathway." (PMID 33673232, 2021). "BI 836845, a humanized IgG1 monoclonal antibody, binds IGF1 and IGF2, thereby inhibiting downstream signaling essential for survival and tumor growth." (PMID 34440844, 2021). "While, in HNCHPV−, expression of RTKs increases following PI3K treatment, in HNCHPV+, tumor cells acquire resistance to isiPI3K by the secretion of IGF2 to activate IGF1R." (PMID 34067117, 2021).
tumor (continued). "VEGF was activated by HIF1 and IGF2 in the tumor angiogenesis process, which led to tumor progression and metastases." (PMID 34067437, 2021). "IGF2 transcription is subject to genomic imprinting, however there is extensive evidence for the dysregulation of this gene in human tumours including HCC, where it is epigenetically regulated." (PMID 34062786, 2021). "IGF2 signals through IGF1R, which is one of the crucial receptor tyrosine kinases implicated in tumor development." (PMID 33407516, 2021). "IGFBP-3 in esophageal cancer cells acts as an antioxidant, thereby enhancing tumor cell growth in an IGF-2-independent mechanism." (PMID 32850012, 2020). "For example, there is a differential methylation of the IGF2 exon 9 CpG cluster, which is hypomethylated in tumor tissues but hypermethylated in normal paired tissues." (PMID 33216823, 2020). "In turn, IR-A–mediated biological responses are regulated by tumor stroma components, such as the proteoglycan decorin, which negatively modulates IGF-2 actions while leaving unaffected insulin/proinsulin effects." (PMID 33364239, 2020). "The resected tumor specimen was positive for IGF2 staining, and big-IGF2 (11–18 kDa) was detected in preoperative serum and tumor samples; the patient was diagnosed with NICTH due to an IGF2-producing tumor." (PMID 32393233, 2020). "In conclusion, we describe a tumor suppressor role of miR-100 and miR-125b in association with CSCs of HCC that involves the inhibition of IGF2 expression and resultant suppression of the IGF2-mediated PI3K/AKT/mTOR pathway." (PMID 33293585, 2020). "IGF-2, which is present in tumor cells, can be secreted by activated STAT3 to impair the antitumor efficacy of anti-IGF-2 therapy." (PMID 32398034, 2020). "Studies conducted on various types of tumor cells have shown IGF-2 overexpression and increased IGF-1R receptor prevalence." (PMID 32850012, 2020). "Ganitumab, a human monoclonal antibody to IGF-1R can enhance the therapeutic effect of platinum-based chemotherapy passing through the inhibition of the IGF-2-dependent tumor growth." (PMID 32498447, 2020). "IGF-2 is a multifunctional cell proliferation regulation factor, which plays an important role in cell differentiation, embryo growth and development, and tumor cell proliferation." (PMID 32398034, 2020). "Stable cell line of miR-100 and miR-125b overexpression decreased IGF2 expression and inhibited tumor growth in the xenograft model." (PMID 33293585, 2020). "To address this need, we focused the present study on analyzing the DNA methylation patterns of the IGF2 gene in paired (Normal/Tumor) tissues obtained from BC patients from different ethnic groups." (PMID 33216823, 2020). "Protein levels of Gli1, Myc, and IGF2 were significantly downregulated as well in LIN28B-AS1 KO tumor tissues, with IGF2BP1 protein levels unchanged." (PMID 32917856, 2020). "Both IGF-1 and IGF-2 appear to play important roles in bone colonization and expansion by metastasizing tumor cells." (PMID 33364239, 2020). "Insulin also induces the overstimulation of receptors of insulin-like growth factor-1 and 2 (IGF-1 and IGF-2), a key promoter of tumor development." (PMID 33238496, 2020). "In preoperative serum and tumor samples, big-IGF2 (11–18 kDa) was detected, and such aberrant IGF2 disappeared." (PMID 32393233, 2020). "Mouse astrocytes expressed very low amounts of Igf1 and Igf2 mRNA, while in HAs both Igf1 and Igf2 mRNA levels were higher than in tumor cells, but still lower than in pericytes." (PMID 32534480, 2020). "Tumor cells produce IGF-2, which has the ability of autocrine and paracrine stimulation of the IGF-1R receptor." (PMID 32850012, 2020). "MiR-483 gene, which is located at 11p15.5 within the second intron of IGF2 gene, is overexpressed in ACC in correlation with the well documented IGF2 overexpression in this type of tumors, suggesting the tumor origin of circulating miR-483-5p." (PMID 32204444, 2020).
tumor (continued). "The data suggested potential tumor suppressor roles of miR-100 and miR-125b, possibly through inhibition of IGF2 expression." (PMID 33293585, 2020). "The four main molecular subtypes of BWS (KCNQ1OT1:TSS-DMR-LOM, H19/IGF2:IG-DMR -GOM, UPD, and CDKN1C mutations) are characterized by specific genotype-phenotype correlation to tumor development risk." (PMID 33101381, 2020). "In SS, the translocation induces the expression of IGF2, which is also required for tumor growth in vivo, while its immune targeting inhibits tumor growth and metastasis formation in ARMS." (PMID 31970591, 2019). "During BI 885578 oral therapy, they observed significant inhibition of tumor growth in the IGF2-high models, with tumor growth inhibition values between 54–92%." (PMID 31623387, 2019). "Activation of the IGF2 pathway has been described in several pediatric tumor entities, and preclinical findings using inhibitors of the IGF axis have demonstrated antitumor activity." (PMID 31234291, 2019). "The authors suggest the use of combined CRC therapies and provide evidence for the role of IGF2 as a biomarker of reduced tumor sensitivity to anti-EGFR therapy as well as a determinant of response to combined IGF2/EGFR targeting." (PMID 31623387, 2019). "Common IGF2 expression by tumor cells as well as autocrine action of this growth factor were also brought to attention, occasionally even reaching target tissues and causing tumor-induced hypoglycemia." (PMID 31623387, 2019). "To evaluate Igf2r tumour suppressor function, we utilised intestinal adenoma models known to be Igf2 dependent." (PMID 31388182, 2019). "In order to further evaluate the potential tumour suppressor function of Igf2r dependent IGF2 regulation, we utilised Igf2rI1565A/+p in a human early stage cancer mouse model." (PMID 31388182, 2019). "We found that miR-493-5p mediated part of its tumor-suppressor activity by abrogating overexpression of insulin-like growth factor 2 (IGF2) and the IGF2-derived intronic oncomir miR-483-3p in HCC cells characterized by IGF2 loss of imprinting (LOI)." (PMID 31320614, 2019). "There are also some results considering IGF2 as an important tissue marker in tumor progression in CRC with liver metastases." (PMID 31623387, 2019). "An interesting study using tumor type-specific analyses uncovered that enhancer-hijacking is the main mechanism mediating the dysregulation of IGF2 locus in CRC." (PMID 31623387, 2019). "To determine the broad application of this CRIST assay, we also mapped noncoding RNAs in tumor-associated genes, including the proto-oncogene FLI1 and the fetal mitogen insulin-like growth factor II (IGF2)." (PMID 31315906, 2019). "We found that demethylating treatment was able to reverse IGF2-miR-483 locus overexpression in tumor cells, evidenced by the decreased expression of IGF2 and miR-483-3p/5p in response to 5-AZA exposure." (PMID 31320614, 2019). "The insulin-like growth factor 2 (IGF2) mRNA binding protein IMP2 (IGF2BP2) is an oncogenic protein known to be overexpressed in different tumor types." (PMID 31261900, 2019). "Studies on the role of microRNAs (e.g., miR-483 and miR-486-5p) as tumor inducers in CRC confirm the involvement of the IGF2 pathway in CRC cell proliferation and invasion both in vitro and in vivo." (PMID 31623387, 2019). "The IGF2 system represents a crucial pathway in the tumor biology of ACC and was considered an attractive target for the treatment of these tumors." (PMID 31378849, 2019). "In transgenic mice, in which HCC was the most common tumor, IGF2 levels were 20-fold higher than in healthy control mice." (PMID 29702590, 2018). "As a consequence, hybrids formed by IR-A dimers are expected to have a higher affinity for IGF-2, thus further increasing the tumor progression abilities of the TC progenitors." (PMID 30513575, 2018). "Taken together, these results showed that the MMP‐1 secreted by highly tumor‐tropic MSCs cleaved IGF‐2/IGFBP2 complex." (PMID 29321953, 2018).
tumor (continued). "The activation of the IGF-2/IR-A loop has a recognized role in tumor progression, de-differentiation, and resistance to therapies." (PMID 30513575, 2018). "In the present case, the tumor expressed both IGF2 and IGF2R; however, IGFR1 was unexpectedly downregulated." (PMID 30168002, 2018). "In conclusion, the present tumor determined to be malignant SFT demonstrated high IGF2 production corresponding to NICTH." (PMID 30168002, 2018). "When separated by tumor type, both ERβ and IGF2 are expressed in similar levels within TNBC and Lum A cancers." (PMID 30338035, 2018). "IGF2 was overexpressed in the present tumor upon both Western blot analysis and immunohistochemistry." (PMID 30168002, 2018). "Taken together, these results showed that IGF‐2 signaling is important for MSC migration toward tumor cells." (PMID 29321953, 2018). "For patients whose tumor epithelial compartment demonstrated IGF2 expression equal to or above the median for the cohort, the risk of disease progression or death was approximately doubled." (PMID 29455465, 2018). "Ectopic expression of miR-483 induces upregulation of IGF2 expression, as well as an increase in tumor cell proliferation, migration, invasion, and tumor colony formation." (PMID 29471827, 2018). "The objective of our study was to evaluate tumor IGF2 expression in a cohort of patients with UCS and determine the relationship of IGF2 with clinicopathologic risk factors, and with disease progression and survival." (PMID 29455465, 2018). "We next investigated the relationship between tumor IGF2 expression and the survival of patients diagnosed with primary GBM." (PMID 30231881, 2018). "Next, we aimed to identify the source of insulin and IGF-1 receptors ligands, namely IGF-1 and IGF-2, in the tumor microenvironment." (PMID 29367764, 2018). "IGF2 was strongly upregulated in the tumor upon immunohistochemistry, consistent with the report of NICTH." (PMID 30168002, 2018). "In this report, we used a CRISPR Cas9-guided chromatin immunoprecipitation assay to characterize the molecular components that participate in the control of IGF2 gene expression in human tumor cells." (PMID 27486969, 2017). "Ectopic expression of miR483 induced upregulation of IGF2 expression, in parallel with an increase in tumor cell proliferation, migration, invasion, and tumor colony formation." (PMID 27486969, 2017). "Insulin-like growth factor binding protein 2 (IGFBP2) binds insulin, IGF1 and IGF2 in circulation, thereby modulating cell survival, migration, and invasion in neoplasms." (PMID 28410230, 2017). "We examined if the miR483-mediated upregulation of IGF2 would affect cell proliferation in transfected tumor cells." (PMID 27486969, 2017). "In TC, the activation of the autocrine IGF-2/IR-A loop was found to correlate with cellular dedifferentiation and tumor progression and aggressiveness." (PMID 29184536, 2017). "Insulin-like growth factor 2 (IGF2), a growth factor, stimulates tumor growth via autocrine or endocrine pathways." (PMID 27802187, 2017). "On the other hand, the IGFBP3 is known to bind IGF1 as well as IGF2 and have an anti-tumor effect in several types of cancers and its concentration decreases markedly in circulation of cancer patients." (PMID 28223541, 2017). "Insulin-like growth factor binding protein 2 (IGFBP2), an important member of the IGFBP family of proteins, binds insulin, IGF1 and IGF2 in circulation, thereby modulating cell survival, differentiation, migration, and invasion in neoplasms." (PMID 28410230, 2017). "It has been demonstrated that in case of PCa, the tumor-distant and -adjacent tissue samples possess higher IGF2 protein expression than the tumor itself and display also IGF2 LOI." (PMID 29017567, 2017). "IGF-2 is a member of the insulin-like growth factor system (IGFs), and IGF-2 stimulates cell proliferation and affects the growth and differentiation of tissues and organs to promote tumor formation." (PMID 27404636, 2016).